PVT1 (Pvt1 oncogene)
Diseases named in the same sentence as PVT1 in open-access papers (continued):
Sharing a sentence is not in itself a finding about the gene and the disease.
cancer (continued). "Furthermore, there is a synergistic effect of positive feedback between MYC and PVT1, which results in increased expression levels of these genes in cancer." (PMID 31309249, 2019). "Interestingly, differential processing of lncPVT1 in various cancers can also increase or decrease levels of PVT1-derived miRNAs, which can inhibit downstream targets." (PMID 31508377, 2019). "Depending on cancer type, different miRNAs appear important in the action of PVT1 in cancer." (PMID 31249809, 2019). "The prognostic values of PVT1 were also investigated in multiple cancer types in multiple cohorts." (PMID 31598169, 2019). "Studies in other cancers support the involvement of PVT1 in cisplatin resistance." (PMID 32039022, 2019). "Moreover, GWAS also indicated that PVT1 and MYC located in the 8q24 segment are associated with cancer risk." (PMID 31309249, 2019). "Similar functional studies of PVT1 can also be found in other types of cancers." (PMID 31598169, 2019). "Third, since most studies report positive results and negative results are rarely published, the results of this study may overestimate the effect of PVT1 on cancers to a certain extent." (PMID 30083911, 2019). "PVT1 is located in the cancer-related region, chromosome 8q24, upstream of the oncogene MYC." (PMID 30679629, 2019). "Targeted PVT1 knockout can be utilized to improve radiotherapeutic sensitivity, inhibit cancer metastasis, block the growth of cancer in vivo, promote cancer cell apoptosis, and reverse drug resistance." (PMID 31497532, 2019). "We and others are progressively uncovering the fact that these transcripts of PVT1 are differentially expressed in various cancers, and may have different functions." (PMID 31877167, 2019). "PVT1 is considered an indicator of poor prognosis in cancer because PVT1 has been shown to play a role in cell proliferation, cell apoptosis, and cell migration, which are key elements of poor prognosis in human cancer." (PMID 31309249, 2019). "The data presented here show that PVT1 exon 9 has a role in cancer initiation, progression, and castration resistance in PCa, and may have clinical applications as a therapeutic target or a diagnostic biomarker." (PMID 31766781, 2019). "PVT1 significantly promotes cell replication, proliferation, and growth in cancer." (PMID 31249809, 2019). "It was reported that Bcl2 can determine the resistance of 5-Fu in carcinoma; hence, we supposed PVT1 may possibly enhance 5-fu resistance in GC via its promotion to Bcl2." (PMID 31205469, 2019). "Recent studies indicate that co‐amplification of human MYC proto‐oncogene, bHLH transcription factor (MYC) and PVT1 is correlated in primary human tumors and that the gain of PVT1 long non‐coding RNA (lncRNA) expression is required for high MYC protein levels in 8q24‐amplified human cancer cells." (PMID 30341811, 2018). "Given that the increase in apoptosis and necrosis in uncontrolled proliferating cells is an important therapeutic goal in cancer, perhaps lncRNA PVT1 inhibition using antisense LNA GapmeRs technology, could have a potential to treat AEL." (PMID 30046623, 2018). "Intriguingly, these genes are up-regulated in cancers exhibiting high Pvt1 expression, suggesting that this gene expression module may commonly be up-regulated in highly proliferating cell populations." (PMID 30456373, 2018). "PVT1 functioned as an oncogenic lncRNA in multiple types of cancers." (PMID 30008615, 2018). "Some autophagy-modulated lncRNAs described in this review are very specific with identical tissue types, for example HULC, PCA3, PVT1 may serve as a potential biomarkers and target therapy in identical cancer types." (PMID 30693021, 2018). "By performing the principal component analysis (PCA) using the feature abundance levels of all the PVT1 isoforms across normal and cancer samples, the authors found that two principal components (PCs) were able to explain more than the 80% of the variance of the data." (PMID 30200360, 2018).
cancer (continued). "PVT1 was found to be co-amplified in more than 98% of cancers with a MYC copy number increase." (PMID 30217017, 2018). "PVT1 overexpression has been identified as predictor for many carcinomas." (PMID 30008615, 2018). "A recent study illustrated that some MYC-driven cancers are dependent on PVT1 activity, as PVT1 could stabilize MYC protein levels by preventing MYC phosphorylation." (PMID 29113413, 2017). "The present study aimed to analyze the differential expression of PVT1 between types of cancer and corresponding normal tissue, explore the effect of PVT1 on cancer diagnosis with TCGA data, and further pool the cancer diagnosis and detection effect of PVT1 by meta-analysis." (PMID 29088881, 2017). "Interestingly, such a sponge mechanism resulted completely abolished in cancer tissues, although both PVT1 and the miR-200 family members appeared up-regulated in the pathological condition." (PMID 28187158, 2017). "Therefore, we conducted a systematic review and quantitative meta-analysis to investigate the prognostic value of PVT1 expression as a prognostic biomarker in various cancers." (PMID 29348896, 2017). "PVT1 locates at 8q24 in the human genome, a region that is usually amplified in some cancers." (PMID 29244840, 2017). "Indeed, UCA1, PVT1 and H19 can serve as a molecular marker for lymph node metastasis in various cancers." (PMID 28410241, 2017). "As a result, these findings indicated that PVT1 may act as a promising prognostic biomarker to predict patients’ survival in different types of cancers." (PMID 29348896, 2017). "Knockdown of PVT1 could inhibit ESCC cancer cell proliferation and migration in vitro as well as tumorigenesis in vivo." (PMID 28404954, 2017). "The expression of PVT1, especially tested in serum, might be a biomarker for cancer diagnosis / detection." (PMID 29088881, 2017). "Interestingly, PVT1 is found co-amplified with MYC in a high percentage of cancers carrying an amplification of the chromosomal region 8q24.21." (PMID 28704924, 2017). "Accumulating evidences indicated that PVT1 can regulate many cancer-related cellular processes, including growth, proliferation, apoptosis, and differentiation, and it contributes to tumorigenesis by participating in DNA rearrangements, encoding microRNAs, and interacting with MYC." (PMID 29348896, 2017). "The PVT1 gene is frequently up-regulated in many types of cancers, including HNSCC." (PMID 29262850, 2017). "We therefore speculated that PVT1 may regulate ESCC cancer progression through silencing of specific miRNA and found that miR-203 was up-regulated after knockdown of PVT1." (PMID 28404954, 2017). "In addition, the prognostic value of PVT1 expression in DFS was evaluated for 5 studies including 676 cancer patients." (PMID 29348896, 2017). "Also, the PVT1 expression level was markedly correlated with the TNM stage of ESCC cancer patients and tumor differentiation state." (PMID 28404954, 2017). "Moreover, dysregulation of PVT1 expression is significantly correlated with certain clinicopathological characteristics of cancer." (PMID 29348896, 2017). "Although MYC is an established oncogene, PVT1 is also emerging as a prominent player in cancer." (PMID 29113413, 2017). "For example, lncRNA PVT1 showed significant amplification and overexpression in 12 cancer types." (PMID 29657279, 2017). "In recent years, a large amount of studies proved that abnormal expression of lncRNAs such as H19, MALAT1, HOTAIR, PVT1, may contribute to cancer development." (PMID 28938549, 2017). "More importantly, PVT1 could be steadily detected in patient’s body fluid including blood and saliva, and might be a noninvasive biomarker for cancer diagnosis and detection." (PMID 29088881, 2017).
cancer (continued). "The mechanism and function of PVT1 have been studied in various cancers." (PMID 27813492, 2016). "Overall, MYC overexpression and PVT1 up-regulation have been reported for several human cancers." (PMID 27366943, 2016). "In the tumor network, PVT1 competing for cancer related genes such as BRCA1, NOTCH2 and CDK1/4." (PMID 27580177, 2016). "For example, PVT1 was found to be up-regulated in nine different cancer types." (PMID 27147563, 2016). "In the KICH tumor state, the competitive activity of PVT1 mainly mediated the ‘Genome Instability and Mutation’ and ‘Insensitivity to Antigrowth Signals’ hallmark processes, while no cancer hallmark process was targeted by PVT1 in the normal state." (PMID 27580177, 2016). "Except that H19 could promote ESCC cell proliferation and metastasis, PVT1 as a rising star among oncogenic lncRNAs has been reported in plenty of cancers." (PMID 27966444, 2016). "Since TET overexpression was already observed in different cancers, such misregulation could be responsible for the hypomethylation of PVT1 promoter in KIRC." (PMID 27366943, 2016). "Although the mechanism by which PVT1 influences disease processes has been studied in multiple cancer types, its role in cervical tumorigenesis remains unknown." (PMID 27232880, 2016). "PVT1 lncRNA also has two isoforms, uc003ysl. and uc010mdp.1, and both of them are significantly overexpressed (adjusted P-values < 1E-10) in the cancer subset (TPM = 1.33 and 0.55, respectively) with respect to adjacent normal tissues (TPM = 0.03 and 0.03, respectively)." (PMID 26602695, 2016). "It is possible that the risk-related SNPs on 8q24 may control expressions of the encompassed lncRNAs, PCAT1, PRNCR1, and PVT1, in PC cells and further contribute to cancer progression." (PMID 26690121, 2015). "Various reports have presented evidence that PVT1 contributes to cancer pathophysiology." (PMID 25624916, 2015). "While the role of MYC in cancer has been proved beyond any doubt, the presence of this famous neighbor together with the enigmatic noncoding nature of PVT1 has hampered prompt recognition that another important oncogene coexisted with MYC in the 8q24 risk region." (PMID 25883951, 2015). "We speculate that the withdrawal in cancer of the PVT1 ceRNA activity can be due to the preferential expression of the two isoforms missing the binding sites for the mir-200 family." (PMID 25033876, 2014). "the sponge program orchestrated by PVT1 results completely abolished in cancer." (PMID 25033876, 2014). "Out of three lncRNAs selected among those previously demonstrated to be essential for BC cell growth, PVT1 emerged as the most significantly associated with BC prognosis, since its overexpression correlated with worse overall survival in TCGA and TARGET Pan Cancer patients." (PMID 39922814, 2025). "In addition, future work has to determine if this tumor-dominant expression of PVT1 is a common phenomenon of MYC-copy-increased cancers as that might pave the way for the development of “off-the-shelf” vaccines against many cancers." (PMID 38731892, 2024). "Functional experiments demonstrated that PVT1 could stabilize the expression of HIF2α by regulating the ubiquitination-dependent degradation pathway, thereby promoting the invasion and metastasis of cancer cells." (PMID 37263709, 2023). "Additionally, BMSC-derived EVs could encapsulate and translocate PVT1 in OS cells, and PVT1 promoted cancer development and migration by binding to miR-183–5p and facilitating the expression of ERG." (PMID 36211364, 2022). "PVT1 is one such lncRNA located on chr8q24.21 that is expressed at low levels in normal tissues but is also designated as an oncogene because of its amplification/up-regulation status in multiple cancers acting as a potential competing endogenous RNA for miRNAs." (PMID 35820706, 2022). "Furthermore, some studies have suggested that PVT1 is a mediator of cancer progression." (PMID 35664988, 2022).
cancer (continued). "In this review of a large number of studies on PVT1, we found that PVT1 is closely related to tumor onset, proliferation, invasion, epithelial–mesenchymal transformation, and apoptosis, as well as poor prognosis and radiotherapy and chemotherapy resistance in some cancers." (PMID 36195846, 2022). "Dysregulated lncRNA score and PVT1 expression may be involved in cancer." (PMID 33910638, 2021). "In addition, EZH2, which was recruited by PVT1, could act as an oncogenic gene in several types of cancer." (PMID 33910638, 2021). "Additionally, PVT1 is related to miRNAs in cancer development." (PMID 34200314, 2021). "Furthermore, we examined the potential of PVT1 to promote cancer development." (PMID 34336125, 2021). "In addition, the role of PVT1 in cancer development is closely related to miRNAs." (PMID 34336125, 2021). "However, PVT1 is also frequently disrupted by recurrent translocations or deletions in many cancer types, including MB, suggesting that it may have additional regulatory functions." (PMID 34316694, 2021). "Then, we detected whether PVT1 was differently expressed in human cancer." (PMID 33391456, 2021). "PVT1 could involve in the development and progression of cancer, and could play an oncogenic role." (PMID 33188158, 2020). "This indicated that PVT1 may act as an oncogene in GBC as in other cancers." (PMID 33067424, 2020). "Moreover, up-regulation of PVT1, comparing with down-regulation of PVT1, might have poor prognosis in various cancers." (PMID 31897242, 2020). "Furthermore, recurrent structural rearrangements of the PVT1 locus disrupts PVT1 transcription in cancer genomes, indicating that the PVT1 locus has unknown regulatory mechanisms." (PMID 32194627, 2020). "To generalize, PVT1 might exert its molecular function via regulating the expression of related genes and miRNA, affecting carcinogenic signaling pathways, which might induce malignant carcinoma." (PMID 31897242, 2020). "Although PVT1 is a nonprotein encoding gene, the fusion of other genes may produce abnormal protein that participates in the cancer process." (PMID 31309249, 2019). "Therefore, PVT1 is very likely involved in cancer cell growth and survival in human cancer." (PMID 31249809, 2019). "The biological effects of PVT1 in cancer may occur through sponging miRNA directly." (PMID 31497532, 2019). "Therefore, we adequately understand that PVT1 and c-Myc jointly regulate key molecules, which may contribute to the development of new and selective anti-cancer drugs for the targeted therapy of cancers with high expression of PVT1 and c-Myc." (PMID 31309249, 2019). "Furthermore, the significance of PVT1 in the metastasis, clinical stage and prognosis of respiratory system tumors is more obvious and can be used as a potential molecular marker to evaluate the prognosis of cancer." (PMID 30083911, 2019). "Both human PVT1 and MYC are located at the 8q24 locus, a well-known cancer-associated chromosome segment and a common and preferred integration site for somatic cell expansion in many cancers, such as prostate, colorectal, breast, ovarian, and cervical cancers." (PMID 31309249, 2019). "In addition, the Fagan’s nomogram showed circulating PVT1 could raise the probability of cancer detection by 25.1% (post-test probability 45.1% - pre-test probability 20%), which was similar to effect practiced in tissue." (PMID 29088881, 2017). "PVT1, especially in serum, might be a usable biomarker for cancer diagnosis / detection." (PMID 29088881, 2017). "Therefore, PVT1 may potentially be used as a novel biomarker for predicting patients’ prognosis in different types of cancers." (PMID 29348896, 2017).
cancer (continued). "In TCGA database, PVT1 could be detected in all included cancers." (PMID 29088881, 2017). "PVT1 might act as an effective biomarker for cancer diagnosis/detection." (PMID 29088881, 2017). "Since PVT1 can act as an important oncogenic driver in many cancers, and it may also help identify ccRCC patients as serum biomarker, we are eager to figure out whether it can play important roles in the carcinogenesis of ccRCC and why it can exert regulatory functions in ccRCC." (PMID 29156724, 2017). "Therefore, PVT1 is a common oncogenic lncRNA participating in tumor development and could be used as a biomarker for cancer detection / diagnosis." (PMID 29088881, 2017). "The drastic change observed in the sponge program, which is suggestive of a marked ceRNA rewiring that characterizes the cancer state, could support the testable hypothesis of a titration mechanism regarding the two main isoforms of PVT1 and the miR-200 family members." (PMID 28187158, 2017). "However, the anti-apoptotic signature induced by PVT1 in other cancer cell types may indicate that its contribution to cisplatin resistance is more far-reaching." (PMID 27232880, 2016). "Thus, we formulated an alternative hypothesis for the abolishment of the ceRNA activity of PVT1 in cancer, prompted by the existence of multiple isoforms produced by its genomic locus." (PMID 25883951, 2015). "Moreover, aberrant overexpression of PVT1 has been discovered in many different human cancers." (PMID 27077133, 2015). "Hence, the observed withdrawal in cancer of the PVT1 sponge activity may be due to the preferential expression of these two isoforms, independently from the abundance of PVT1." (PMID 25883951, 2015). "Hence, the observed withdrawal in cancer of the PVT1 sponge activity may be due to preferential expression of these two isoforms, independently from the abundance of PVT1." (PMID 25033876, 2014). "In summary, we identify PVT1 as a complex molecular hub that orchestrates the interplay between MYC, mTOR, AKT, and RAS signaling in cancer." (PMID 40027648, 2025). "In terms of adjuvant therapy, KLT increases cancer cell sensitivity to chemotherapeutics via JAK2/STAT3 and NF-κB pathway modulation, downregulating MDR1, MRP1, and PVT1, while mitigating chemotherapy-related adverse effects." (PMID 41164166, 2025). "Specific lncRNAs such as PVT1, LINC00853, LINC00592, ZNF571-AS1, and SEPSECS-AS1 have been highlighted for their roles in cancer, with their expression levels varying across cancer types and individuals." (PMID 41335135, 2025). "In summary, CENP-H is involved in cancer growth and metastasis through PI3K/AKT, survivin, and mitochondrial apoptosis signaling mechanisms and can be regulated by lncRNA PVT1/miR-612, Sp1, or Sp3." (PMID 40071086, 2025). "In conclusion, our data collectively implicate PVT1 as a crucial hub regulating MYC potency by modulating both AKT and MAPK activity in human cancer." (PMID 40027648, 2025). "CENP-H can promote cancer growth and metastasis through PI3K/AKT, Survivin, and mitochondrial apoptosis signaling mechanisms, and it can be regulated by lncRNA PVT1/miR-612, Sp1, or Sp3." (PMID 40071086, 2025). "LncRNA PVT1 is upregulated in NSCLC tissues, and its knockout significantly inhibits cancer cell viability and invasion in xenograft mouse models while inducing apoptosis." (PMID 40746614, 2025). "At the MYC locus (chr8:127–130 Mb), which is subject to cell type–specific enhancer regulation across cancers, H3K27ac HiChIP revealed extensive E-P interactions in control cells linking MYC to PVT1 and CCDC26." (PMID 41509392, 2025). "The MYC 8q24 locus has been demonstrated to express cancer-specific lncRNAs, including CCAT1 and PVT1." (PMID 38763947, 2024). "On the one hand, PVT1 and MYC locate at chromosome 8q24, which leads to co-amplification of them in various types of cancer." (PMID 39376555, 2024).